IL6 (interleukin 6)
Diseases named in the same sentence as IL6 in open-access papers (continued):
Sharing a sentence is not in itself a finding about the gene and the disease.
endometritis (71 papers, 2012 to 2025). An acute or chronic, usually bacterial infectious process affecting the endometrium. "For instance, IL1β is significantly upregulated in PBIE in susceptible mares, while IL6 or TNFα are predominant in chronic subclinical endometritis and overexpression of IL1β, IL6, and TNFα is observed in subacute suppurative endometritis." (PMID 37869492, 2023). "Meanwhile, endometritis caused by bacterial infection usually involves inflammatory factors such as IL-1β, IL-6, and TNF-α." (PMID 36846263, 2023). "Many studies showed that endometritis in mares was associated with clear changes in the expression pattern of pro-inflammatory cytokines such as IL-6 and prostaglandins in the uterine tissue samples." (PMID 35042518, 2022). "Uterine infections increase expression of mRNA transcripts in the endometrium that encode molecules associated with inflammation, such as the cytokines IL-1β and IL-6, and the chemokine IL-8." (PMID 24209779, 2013). "Previous studies by Fumuso and co-workers showed that mares susceptible to persistent endometritis had significant upregulated cellular immune response (IL-1β, IL-6, TNF-α and IL-8) and down-regulated anti-inflammatory activity (IL-10) compared to resistant mares at estrous baseline levels." (PMID 22458733, 2012). "In summary, the present study provided strong evidence of the protective effects of TREM‐1 deficiency against LPS‐induced endometritis in mice, the mechanism of which could be deduced as knocking out of the Trem‐1 inhibited the LPS‐induced production of IL‐1β, IL‐6 and TNF‐α." (PMID 31365951, 2019). "The previous study showed that in the patients with endometritis, the cyclic GMP–AMP synthase(cGAS)-STING pathway was activated and the expression of cytokine-encoding genes, including IL-1β, IL-8, IL-6 and IFN-β1 were increased." (PMID 39992946, 2025). "Berberine and carvacrol, respectively, were found to significantly reduce the expression of TNF-a, IL-1β, IL-6, and IL-8 after treatment of endometritis in mice, and the differences were significant compared with those in the model group (p < 0.01)." (PMID 40431224, 2025). "Numerous inflammatory mediators, including tumor necrosis factor α (TNF-α), and interleukin (IL)-1β, IL-6, and IL-8, are released during endometritis, and inhibition of these inflammatory factors can effectively reduce the severity of bacterial endometritis." (PMID 40431224, 2025). "The results showed that the TCMF significantly alleviated the symptoms of endometritis, reduced epithelial sloughing in the uterus, and significantly lowered the mRNA levels of IL-1β and IL-6 in uterine tissue." (PMID 41002185, 2025). "LPS challenge triggered a robust upregulation of il1b, tnfa, and il6 in WT mice, confirming the successful induction of endometritis." (PMID 41583494, 2025). "Studies have found that Escherichia coli increases inflammatory factors, such as iNOS, IL-1β, TNF-α, IL-6, etc., through the NF-κB signaling pathway, leading to endometritis." (PMID 40514455, 2025). "One study using Biochemical Decoction to treat LPS-induced endometritis found that IL-1β, IL-6, and IL-8 levels were significantly reduced in the treatment group compared to the LPS group." (PMID 41002185, 2025). "TNF‐α, IL‐1 and IL‐6 are the main pro‐inflammatory cytokines, and their levels reflect the severity of endometritis." (PMID 39042561, 2024). "The results showed that S. aureus significantly increased the levels of MPO, TNF‐α, IL‐1β and IL‐6 in uterine tissue, and increased the expression of p‐p65 and p‐IκBα proteins in uterine tissue to induce endometritis in mice (p < 0.05)." (PMID 39042561, 2024). "Other studies reported that a mouse model of endometritis that was injected with LPS in the uterus showed that LPS significantly increased the expression of Il-6." (PMID 38396694, 2024). "Increased inflammatory cytokines TNF-α, IL-6, and IL-1β were observed in patients with endometritis." (PMID 38169293, 2024).
endometritis (continued). "Numerous studies have demonstrated that LPS stimulates the production of IL-6, IL-1β, and TNF-α, which are also implicated in the pathogenesis of endometritis." (PMID 37570258, 2023). "Three examined cytokines, including IL-1, IL-1β, and IL-6, were found to have increased gene expression in buffaloes with endometritis compared to healthy animals." (PMID 37368756, 2023). "In LPS-induced endometritis in mice, alpinetin exerts its anti-inflammatory effects by inhibiting the expression of IL-6, IL-1β, and TNF-α." (PMID 37570258, 2023). "IL‐6 was found to play a predominant role in immune response in mares resistant to persistent breeding‐induced endometritis (PBIE), determining proper inflammatory reaction." (PMID 35182075, 2022). "This study aimed (I) to identify and characterize EVs from low volume uterine lavage (LVL) and serum in mares with endometritis, compared to healthy controls and (II) to measure serum levels of interleukin 6 (IL-6), and prostaglandins (PGF2α and PGE2)." (PMID 35042518, 2022). "The most important cytokines in case of endometritis seem to be interleukins 1β, 6 and 10 (IL‐1β, IL‐6 and IL‐10), besides tumour necrosis factor α (TNF‐α)." (PMID 35182075, 2022). "Meanwhile, previous studies have shown that TNF-α, IL-6, and IL-1β were upregulated in S. aureus-induced endometritis." (PMID 35937303, 2022). "In this study, we successfully established an endometritis model in mouse using Escherichia coli; endometrial integrity was destroyed, inflammatory cells infiltrated and the expression of IL-6, IL-1β, TNF-α was significantly up-regulated." (PMID 35744807, 2022). "Mice were injected with different concentrations of Escherichia coli (E. coli) for 24 h to establish a model of endometritis, and we detected the mRNA and protein expressions of IL-6, IL-1β and TNF-α in the mouse uterine tissues." (PMID 35744807, 2022). "Previous studies reported that the expression of pro-inflammatory cytokines IL-6 and prostaglandins (PGF2α and PGE2) in the uterine tissue samples were associated with the development of endometritis in cows and mares." (PMID 34199703, 2021). "Serum concentrations of IL-6 showed a significant increase in subclinical and clinical endometritis in cows and ewes." (PMID 34199703, 2021). "We found that the IL-1β and IL-6 levels were significantly elevated in uterine tissues with endometritis." (PMID 35003515, 2021). "In this experiment, bAD-MSCs were co-cultured within a bovine endometrial epithelial cell inflammation model; we found that the levels of IL-1β, TNF-α, and IL-6 were significantly lower than those in the endometritis model group." (PMID 34746277, 2021). "In the present study, the serum concentrations of IL-6 were markedly increased in mares with endometritis compared with healthy mares." (PMID 34199703, 2021). "qRT-PCR results showed that the endometritis tissues secreted the proinflammatory cytokines IL-1β, IL-6, and TNF-α, but there was a decreased secretion of IL-10, an anti-inflammatory mediator." (PMID 34504639, 2021). "Some key inflammatory mediators have been found to be related to the occurrence and development of endometritis, including IL-1β and IL-6.Thus, the expression levels of IL-1β and IL-6 were measured." (PMID 35003515, 2021). "Conversely, upstream regulators including TNF, LPS, interferon, IL‐1β, and IL‐6 were activated in oocytes of bacteria‐infused heifers at Day 60 long after the resolution of uterine infection." (PMID 32821881, 2020). "In contrast, elevated serum and tissue concentrations of pro-inflammatory cytokines, including TNF-α, IL-1β, and IL-6, were observed in cows with metritis, endometritis, or subclinical endometritis." (PMID 33132596, 2020). "In mares with endometritis, the concentrations of IL-6 and TNF-α in supernatants from endometrial tissue cultures were increased, compared with mares that did not suffer from endometritis, however, only in the cases of SSE and not ChE." (PMID 27152525, 2016).
endometritis (continued). "This is in agreement with results of molecular studies performed on the endometria of cows, in which mRNAs for both IL-1β and IL-6 were over-expressed during the course of endometritis." (PMID 27152525, 2016). "Bovine endometrial stromal cell secretion of IL-6 in response to 24-h treatment with 100 ng/ml LPS is a well-established model of endometritis." (PMID 26673142, 2016). "The listed uterine washing tests have shown only slight changes in the concentration of TNF-α, IL-6 and IL-10 in cows with subclinical endometritis." (PMID 25846950, 2015). "This is reflected in the results of our research in the form of elevated levels of proinflammatory IL-6 in uterine washings of cows with endometritis." (PMID 25846950, 2015). "Other studies also showed a higher level of IL-6 mRNA in the uterus of cows with subclinical endometritis compared to healthy cows." (PMID 25846950, 2015). "The uterine washings in cows with subclinical endometritis had significantly higher levels of IL-6, IL-10, and Hp compared to the healthy group (p < 0.001)." (PMID 25846950, 2015). "Cows with subclinical endometritis had higher leptin and IL-6 concentrations compared to normal cows (P < 0.05), whereas IL-1β concentrations were higher in cows with any diagnosed uterine inflammatory conditions compared to normal cows (P < 0.05)." (PMID 24209779, 2013). "Serum concentrations of leptin and IL-6 were lower in cows diagnosed with subclinical endometritis compared to those with metritis or clinical endometritis (P < 0.05)." (PMID 24209779, 2013). "However, pretreatment of luteolin significantly attenuated TNF-α, IL-6, and IL-1β production in S. aureus–induced endometritis mice." (PMID 38169293, 2024). "Furthermore, leonurine effectively reduces levels of inflammatory cytokines, such as tumor necrosis factor-alpha (TNF-α), interleukin (IL)-6, and IL-1β (p < 0.01), which play a crucial role in regulating acute endometritis." (PMID 39062636, 2024). "Moreover, IL-6 has a fundamental role in the uterine intracellular communication resulting in accurate diagnosis of clinical endometritis." (PMID 36930327, 2023). "The findings of a study on the expression of cytokine genes in the uteri of Bubalus bubalis associated with endometritis infection revealed that IL-1 and IL-6 gene expression was upregulated by 1.3, 1.7, and 5-fold, respectively, in endometritis-infected buffaloes compared to control animals." (PMID 37756095, 2023). "Transcription of IL‐6 gene increased along with the increase in inflammation severity, which is in line with recent studies, as it is one of the most important cytokines in endometritis development." (PMID 35182075, 2022). "Additionally, up-regulation of miR-92b improved the outcome of endometritis, as indicated by the mitigated pathological conditions, as well as the down-regulation of IL-6 and TNF-α secretion." (PMID 33867846, 2021). "However, uterine washings demonstrated higher levels of IL-6, IL-10 and HP in cows with subclinical endometritis than healthy cows." (PMID 25846950, 2015). "Furthermore, serum leptin, TNF-alpha, IL-1beta and IL-6 were higher in cows with subclinical endometritis compared to normal cows (P < 0.05), and insulin and IGF-1 concentrations were lower in cows with metritis or clinical endometritis." (PMID 24209779, 2013). "Interestingly, in the present study, IL-6 increased during Weeks 1 and 2 in cows with metritis, and during Weeks 4 and 5 in cows with clinical and subclinical endometritis." (PMID 24209779, 2013). "Endometritis is characterized by the high expression of CD14, TLR4, IL-1α, IL1-β, IL-6, IL-8, and TNF-α in uterine tissue and cervical mucus." (PMID 39858163, 2025). "This study investigates postpartum bovine uterine tissues, comparing inflammatory cytokines (IL-1β, IL-6, TNF-α) and oxidative-stress-related factors (GPx, SOD, CAT) between healthy and endometritis groups." (PMID 40646747, 2025).
endometritis (continued). "The research in this study demonstrated that the transvaginal instillation of a specific amount of LPS induced acute endometritis in mice, leading to increased levels of pro-inflammatory cytokines such as TNF-α, IL-6, and IL-1β." (PMID 39062636, 2024). "✧Relieved the endometritis in BEECs by enhancing the antioxidant response (Nrf2, HO-1, and NGO1) and the downregulation of pro-inflammatory cytokines (TNF-α and IL-6)." (PMID 39408650, 2024). "The results showed that the IL-6, IL-1β, and TNF-α were decreased, and the IL-10 was increased in mice with endometritis treated with naringin." (PMID 39234103, 2024). "In this study, LPS-induced BEND cell inflammation was used to establish a model of endometritis effects of LPS on expression levels of inflammatory factors in BEND cells IL-1β, IL-6, IL-8, TNF-α for further analysis." (PMID 39682333, 2024). "On the other hand, it was reported that the peroxisome proliferator-activated receptor γ (PPARγ) inhibits pro-inflammatory cytokines (TNFα, IL-1β, and IL-6), TLR4, and NF-κB, relieving LPS-induced endometritis in pig endometrial epithelial cells (EECs)." (PMID 39408650, 2024). "The serum levels of Hp, SAA, Cp, IL-6, IL-10, TNF-α, NO and MDA were significantly (P˂0.05) increased, along with reduction of CAT, GPx, SOD and TAC in buffalo–cows with endometritis compared to healthy ones." (PMID 38459095, 2024). "Concerning the APPs and cytokines, the serum levels of Hp, SAA, Cp, IL-6, IL-10 and TNF-α were significantly (P˂0.05) increased in buffalo–cows with endometritis compared to healthy ones." (PMID 38459095, 2024). "And the signaling transduction of PGD2 through the DP1 receptor in bacteria-mediated endometritis in dairy cows was found to suppress activation of NF-κB and P38 MAPK signaling, thus reducing expression of IL-6, IL-1β, and TNF-α." (PMID 37891648, 2023). "Recently, it was reported that serum concentrations of IL-6 and prostaglandins (PGF2α and PGE2) were higher in mares suffering from endometritis compared to healthy ones." (PMID 35042518, 2022). "Herein, the serum levels of IL-6, PGF2α, PGE2, as well as PGE2:PGF2α ratio were higher in mares with endometritis compared with healthy ones." (PMID 35042518, 2022). "In addition, IL-6 levels were found to be greatly increased in uterine tissues of rats with endometritis compared to control rats, and interestingly, in the group with endometritis, treatment with Cl-amidine resulted in a 22% decrease in IL-6 levels in uterine tissue." (PMID 35565576, 2022). "For instance, one study finds that miR‐34a induces the release of the proinflammatory cytokines including IL‐1β, IL‐6, and TNF‐α in endometritis." (PMID 34861059, 2022). "First, we demonstrated that PGD2 inhibited the secretion of the inflammatory cytokines IL-1β, IL-6, and TNF-α to some extent, contributing to inhibition of the phosphorylation of p38, ERK, and NF-κB in bovine endometritis." (PMID 36435808, 2022). "Several studies have found that the mRNAs of interleukin (IL) 1A, IL1B, IL6, IL8, chemokine CXL ligand (CXCL) 3, and CXCL5 are up-regulated in dairy cows with endometritis." (PMID 33718475, 2021). "As far as we know, this is the first report that measures the serum concentrations of IL-6, PGF2α, and PGE2 in mares with endometritis compared to the healthy Arabian mares." (PMID 34199703, 2021). "The results showed that LPS treatment for 12 h significantly increased the levels of IL-6, IL-1β, and TNF‐α, indicating the successful establishment of the LPS-induced endometritis model in mice." (PMID 34976866, 2021). "Previous studies show that mRNA of proinflammatory cytokines interleukin-1 alpha (IL1A), IL1B, IL6, and TNF and expression of chemokines IL8 and CXCL5 increased in endometrial epithelial cells during the estrous cycle and subclinical or clinical endometritis." (PMID 33324700, 2020).
endometritis (continued). "In agreement with our results, IL-1, IL-6, IL-10, and TNF have been found to be significantly downregulated in a mare endometritis model with chronic pathological endometrial changes, including fibrosis, after mesenchymal stem cell treatment." (PMID 29954457, 2018). "Supporting current results, researchers found significant increase in IL-1, IL-6, IL-10, and TNF in a mare model of endometritis with chronic pathological endometrial changes including fibrosis." (PMID 28883083, 2017). "The serum levels of TNF-α and IL-6 (p < 0.01) as well as Hp and SAA (p < 0.001) were higher in cows with subclinical endometritis, while the levels of IL-10 were lower (p < 0.001) compared to the uterine washings." (PMID 25846950, 2015). "The aim of the study was to evaluate the concentrations of proinflammatory cytokines: TNF-α and IL-6, anti-inflammatory cytokine IL-10, and APPs - Hp and SAA, in the serum and uterine washings of cows with subclinical endometritis and healthy animals." (PMID 25846950, 2015). "The results show that the levels of TNF-α (p < 0.01), IL-6, IL-10 as well as SAA and Hp were significantly higher in the serum of cows with subclinical endometritis compared to the controls (p < 0.001)." (PMID 25846950, 2015). "Cows with metritis or clinical endometritis had higher serum concentrations of adiponectin, leptin, TNF-alpha, IL-1beta and IL-6 compared to normal cows (P < 0.05)." (PMID 24209779, 2013). "In this study, postpartum dairy cows diagnosed with metritis, clinical endometritis, or subclinical endometritis had higher serum concentrations of adiponectin, TNF-α, IL-1β and IL-6 compared to normal cows." (PMID 24209779, 2013). "The RT-qPCR analysis of the inflammatory cytokines (IL-1β, IL-6, TNF-α) in the two groups demonstrated that the mRNA expression levels of IL-1β, IL-6, and TNF-α were significantly upregulated in the endometritis group compared to the healthy group (* p < 0.05; ** p < 0.01)." (PMID 40646747, 2025). "The results showed that the mRNA levels of IL-1β, IL-6, IL-8, and IL-18 were significantly reduced in the drug treatment groups compared to the LPS group, which is consistent with results from other studies using TCMF treatments for endometritis." (PMID 41002185, 2025). "Moreover, a study revealed that interferon-tau (IFN-τ) prevents S. aureus-induced endometritis by downregulating the expressions of NF-κB, matrix metalloproteinase 9 (MMP 9), TLR2, TNF-α, IL-1β, and IL-6 levels." (PMID 39408650, 2024). "The inflammatory response to intrauterine adhesions can increase IL-6 and TNF-α in menstrual effluent in the uterus, and GYS treatment significantly reduced expression of the pro-inflammatory cytokines in rats with endometritis." (PMID 38630770, 2024). "In addition, our study also verified the effects of inflammatory cytokines (IL-1β, IL-6, and TNF-α) in the endometritis model." (PMID 36846263, 2023). "Cl-amidine may inhibit the synthesis of pro-inflammatory cytokines (IL-, IL-6, and TNF-) in LPS-induced endometritis, implying that it has therapeutic potential in the prevention of NETs and the treatment of chronic endometritis." (PMID 35565576, 2022). "We aimed (I) to investigate expression profile of eca-miR-155, eca-miR-223, eca-miR-17, eca-miR-200a, and eca-miR-205 (II) and to measure concentrations of interleukin 6 (IL-6), and prostaglandins (PGF2α and PGE2) in serum of mares with healthy and abnormal uterine status (endometritis)." (PMID 34199703, 2021). "Concentrations of IL-6, PGE2, and PGF2α were higher in mares with endometritis compared to control." (PMID 34199703, 2021). "We have shown in our study significantly higher levels of IL-6, IL-10, and Hp in uterine washings of cows with endometritis compared to cows without the disease." (PMID 25846950, 2015).